NPY (neuropeptide Y)
Diseases named in the same sentence as NPY in open-access papers (continued):
Sharing a sentence is not in itself a finding about the gene and the disease.
cancer (continued). "For other genes or regions, e.g. DLX5, GRASP Region 3, IRX1, MMP2, NPY, PDX1 and TCF21, significant levels of methylation were evident in the matched normal tissue but methylation was always significantly increased in the cancer tissue." (PMID 24485021, 2014). "Therefore, to validate these findings, we ectopically expressed either ERK5 or SREBP2 in cancer cells, with or without recombinant NPY, in the presence or absence of ERK5 or SREBP inhibitors." (PMID 40595538, 2025). "Therefore, we measured fatty acid oxidation (FAO) driven oxygen consumption rate (OCR) and glycolytic rate (ECAR) in control (ScrKO) and Y5rKO cancer cells in the presence or absence of recombinant NPY treatment (100 nM)." (PMID 40595538, 2025). "The immune histochemical sections of the HPA database showed that the protein expression of SLPI, DES, IAPP, NPY, ISG15 and HLA-DMB in normal tissue was higher than that in cancer tissue, while the protein expression of PLA2G2A in normal tissue was lower than that in cancer tissue." (PMID 36774376, 2023). "Furthermore, in NB, NPY has been shown to promote cell motility via increased cytoskeleton remodeling, and NPY5R expression was significantly up-regulated in NB cells adjacent to blood vessels, suggesting preferential NPY5R expression in angioinvasive cancer cells." (PMID 40073121, 2025). "Our findings provide evidence for the role of the hypoxia-inducible NPY/Y5R/RhoA axis in promoting genomic changes and subsequent osseous dissemination in ES, and suggest that targeting this pathway may prevent CIN and disease progression in ES and other cancers rich in NPY and Y5R." (PMID 35484119, 2022). "The expression levels of FAIM2, NPY, and FOXE1 were also compared in the cancer samples with normal samples in validation cohort 3 and a negative relationship between methylation and gene expression was observed." (PMID 36329447, 2022).
cardiovascular diseases (28 papers, 2009 to 2025). "The association between circulating NPY and multiple arteriosclerotic cardiovascular disease risk factors, including smoking, obesity, type 2 diabetes mellitus and hypertension, has been revealed." (PMID 39575855, 2025). "Epidemiological evidence indicated that circulating NPY was closely related to multiple arteriosclerotic cardiovascular disease risk factors." (PMID 39575855, 2025). "Raised serum concentrations of the sympathetic co‐transmitter neuropeptide Y (NPY) are linked to cardiovascular diseases." (PMID 37460913, 2023). "Genetic studies have supported the association between NPY polymorphisms and an increased risk of cardiovascular diseases." (PMID 34512386, 2021). "The wide range of involvement of NPY in cardiovascular disease processes makes further study into its associations and actions an exciting prospect." (PMID 30283345, 2018). "Neuropeptide Y (NPY) is an abundant protein in humans that has been implicated in cardiovascular disease pathophysiology, but comprehensive evaluation of the gene coding for this protein has never been pursued in cardiovascular disease." (PMID 19119412, 2009). "The NPY system is strongly associated with arteriosclerotic cardiovascular disease." (PMID 33708805, 2021). "Increasing neuropeptide Y (NPY) has been shown to be a risk factor for cardiovascular diseases." (PMID 31708788, 2019). "A polymorphism in the NPY gene resulting in a change of leucine 7 to proline in the signal peptide is associated with elevated cholesterol levels, higher alcohol consumption, and may be a risk factor for various metabolic and cardiovascular diseases." (PMID 30327597, 2018). "An explanation of how L-type channels contribute to the development of cardiovascular diseases could be due to their stimulation by the signaling of receptors implicated in cardiac and vascular diseases such as those activated by: Ang II, ET-1, neuropeptide Y (NPY), and β-adrenergic agonists." (PMID 37240147, 2023). "Levels of neuropeptide Y (NPY), which is a sympathetic neurotransmitter, are elevated in cardiovascular diseases." (PMID 38087221, 2023). "Substance P and neuropeptide Y are important substrates of DPP4 that can mediate various detrimental effects in cardiovascular diseases." (PMID 35884882, 2022). "Sympathetic nerve terminals, which can act as local neuromodulators in various cardiovascular disorders, represent one of the main sources of NPY." (PMID 36408384, 2022). "Collectively, the effect of NPY on cardiovascular diseases is mainly through the regulation of neurons in neurohumoral microenvironments." (PMID 34344469, 2021). "There is evidence linking NPY to different types of cardiovascular diseases with differential, even opposing, effects via diverse mechanisms." (PMID 31811615, 2020). "The high burden of cardiovascular disease, combined with the pleiotropic influence of NPY, demonstrates the importance of further elucidating the role of NPY in cardiovascular disease processes." (PMID 30283345, 2018). "Neuropeptide Y is an abundant sympathetic co-transmitter, widely found in the central and peripheral nervous systems and with diverse roles in multiple physiological and pathophysiological processes, such as cardiovascular diseases." (PMID 36361795, 2022). "A critical role in the pathogenesis of cardiovascular diseases is now recognized for NPY." (PMID 32930881, 2020). "This may point to the therapeutic implications as suggested for NPY system in other cardiovascular diseases." (PMID 31811615, 2020). "This may point to therapeutic implications as suggested for NPY system in other cardiovascular diseases." (PMID 31811615, 2020). "Therefore, NPY regulation plays a decisive role in the development of cardiovascular disease." (PMID 33708805, 2021). "However, the role of NPY in cardiovascular disease was controversial, and many studies showed that the NPY had negative effects on cardiovascular system." (PMID 39107876, 2024).
neurodegenerative disease (20 papers, 2015 to 2024). A disorder of the central nervous system characterized by gradual and progressive loss of neural tissue and neurologic function. "We further investigated the role of NPY in alleviating ER stress-mediated cell death, which is the most common cause of pathogenesis in many neurodegenerative diseases." (PMID 36429093, 2022). "Our findings correlate with previous studies suggesting the involvement of the NPY system in the aging process, particularly in the brain of mammals, and in association with neurodegenerative diseases through the activation of several mechanisms." (PMID 35409198, 2022). "Neuropeptide Y (NPY), a sympathetic neurotransmitter, is involved in various physiological functions, and its dysregulation is implicated in several neurodegenerative diseases." (PMID 36429093, 2022). "The hippocampus and SVZ are the most active areas of neurogenesis in adult brain, and the stimulative effects of NPY on neural precursor proliferation and differentiation in these regions are likely to ameliorate neuron loss in neurodegenerative diseases." (PMID 29109742, 2017). "NPY stimulates neuronal survival and neuroproliferation, attenuates neuroinflammation, suppresses excitotoxicity, induces autophagy, and counteracts depressive symptoms and weight loss present in neurodegenerative diseases." (PMID 31481869, 2019). "Neuropeptide Y plays functions associated with modulation of food ingestion, mood, learning and memory and also plays an important role in neuroprotection against neurodegenerative diseases." (PMID 30687008, 2018). "As an orexigenic agent, NPY may ameliorate the weight loss in neurodegenerative diseases." (PMID 29109742, 2017). "Neuropeptide Y (NPY), an endogenous peptide composed of 36 amino acids, has been investigated as a potential therapeutic agent for neurodegenerative diseases due to its neuroprotective attributes." (PMID 39114576, 2024). "Studies in humans and rodents have shown that NPY levels in the brain are altered in several neurodegenerative diseases, including AD." (PMID 39585059, 2024). "NPY has previously been shown to contribute to the mitigation of neuroinflammation across various neurodegenerative diseases, primarily through its activation of specific receptors on glial cells." (PMID 39114576, 2024). "The NPY system has therapeutic potential in the most common neurodegenerative diseases because it can attenuate the pathologic mechanisms that lead to neurodegeneration." (PMID 39585059, 2024). "Given the neuroprotective role of NPY and its receptors in neurodegenerative disease, exploring other functional SNPs or the whole exons of these genes in MJD patients is suggested before a definite conclusion is reached." (PMID 35185528, 2022). "To date, the NPY system has been found to play a potential role and to be a therapeutic target in many neurodegenerative diseases, such as AD, PD, and HD." (PMID 35185528, 2022). "One of the endogenous protective systems activated during ischemia and in neurodegenerative diseases is represented by neuropeptide Y (NPY)." (PMID 34292517, 2022). "In contrast, in aged rodents as well as in brain samples from individuals with neurodegenerative disease, the expression levels of NPY and NPY receptors had decreased in several brain areas." (PMID 35409198, 2022). "Neuroprotective effects of NPY have included the improvement of motor deficits and survival in a model of neurodegenerative disease." (PMID 34439588, 2021). "Neuropeptide Y, a 36-amino acid peptide secreted by the hypothalamus, was found to play key roles in neurodegenerative diseases including modulation of neurogenesis, food intake, and thermogenesis." (PMID 32967723, 2020). "Currently, the use of NPY as a therapeutic agent for particular neurodegenerative diseases has been suggested [18, 19, 20; for review, see 21]." (PMID 30984535, 2019).
neurodegenerative disease (continued). "At present, in most animal models of neurodegenerative diseases, NPY exerts its protective effect through different mechanisms." (PMID 31481869, 2019). "In recent years, the effects of NPY on neurodegenerative diseases and the involved mechanisms have been revealed gradually." (PMID 29109742, 2017). "Nevertheless, the results of neuropeptide studies have not yet reached clinical application, so further studies are needed to fully understand the complex role of NPY in preventing or halting the progression of neurodegenerative diseases, as well as the safety of its use in the clinic." (PMID 39585059, 2024). "We found that NPY increased to the highest degree in old mice, which may lead to the occurrence of degenerative diseases due to the disturbance of retinal metabolic regulation." (PMID 38979414, 2024). "NPY can modulate neurogenesis and neurotrophins, increase trophic support, decrease excitotoxicity, and regulate calcium homeostasis, attenuate neuroinflammation, as well as influence the clinical manifestations of neurodegenerative diseases." (PMID 31481869, 2019). "It is believed that NPY can be a potential therapeutic target in neurodegenerative diseases." (PMID 31481869, 2019). "Additionally, NPY also influences the common clinical manifestations of neurodegenerative diseases, such as depression and weight change." (PMID 31481869, 2019). "Besides, NPY displays some ameliorative effects on clinical manifestations of neurodegenerative diseases." (PMID 29109742, 2017). "In fact, a decline of NPY and ghrelin plasma levels in humans correlates with the increase of age and the modulation of these peptides has been shown to provide neuroprotection in several neurodegenerative diseases." (PMID 27441412, 2016). "NPY was initially speculated to be only a neurotransmitter; however, further research in human and animal models has revealed its diverse pathophysiological functions in many neurodegenerative diseases." (PMID 36429093, 2022). "Neuropeptide Y (NPY) signaling has been extensively associated with modulation of pre- and post-synaptic excitatory potentials across multiple brain regions, and has been shown to be neuroprotective by improving motor deficits and survival in models of neurodegenerative disease (see review)." (PMID 34439588, 2021). "The neuronal proliferation induced by NPY occurs via ERK1/2 and Akt pathways, inhibiting necrotic and apoptotic cell death in neurodegenerative diseases." (PMID 36429093, 2022). "After TBI, several ligand–receptor interactions were significantly downregulated, including colony‐stimulating factor signaling, neurotrophic (NT) signaling (BDNF‐NTRK2 interaction), and neuropeptide Y (NPY) signaling, which generally play a neuroprotective role in TBI or neurodegenerative diseases." (PMID 37269057, 2023). "In conclusion, our findings highlighted that NPY attenuates the pro-apoptotic markers involved in glutamate toxicity, ER stress, and oxidative stress in SH-SY5Y cells and strengthens further the concept of NPY as a potential therapeutic target against neurodegenerative diseases." (PMID 36429093, 2022).
psychiatric disorder (20 papers, 2013 to 2025). A disorder characterized by behavioral and/or psychological abnormalities, often accompanied by physical symptoms. "Because the salience network and default mode network are implicated in many psychiatric disorders, we evaluated the impact of NPY expression on those networks." (PMID 34867217, 2021). "NPY is widely distributed in the brain and expressed in regions implicated in psychiatric disorders." (PMID 25206349, 2014). "NPY may exert effects on the risk of development of psychiatric disorders through subtly varied activity in the salience network." (PMID 34867217, 2021). "In the central nervous system (CNS), NPY is considerably involved in numerous behavioral and physiological processes associated with stress and stress resilience, energy homeostasis, cognition, various psychiatric disorders, pain, and the control of food intake." (PMID 38425753, 2023). "These unique characteristics of NPY-KO zebrafish make them suitable experimental animals for studying psychiatric disorders." (PMID 32246073, 2020). "The products of SST and NPY, somatostatin and neuropeptide Y, respectively, often serve as important biomarkers in psychiatric disorders." (PMID 29958387, 2018). "Several lines of evidence link NPY with the psychobiology of resilience to psychiatric disorders and CVD comorbidity." (PMID 25206349, 2014). "Overall these findings suggest that NPY exerts effects on risk for psychiatric disorders primarily through the salience network, and not the default mode network." (PMID 34867217, 2021). "It is known that a dysfunction in the activity of several neurotransmitters and neuropeptides can act as a facilitator for epileptic seizures and psychiatric diseases, as already discussed, and also corroborate our data, in which epileptic animals showed less density of cells expressing PV and NPY." (PMID 34025410, 2021). "NPY, long known as a neuropeptide modulating feeding behavior and energy homeostasis, has been reported influencing neuronal processes relevant in psychiatric disorders." (PMID 31133798, 2019). "Potential findings in NPY synthesis between genders may be relevant to stress-mediated processes and psychiatric disorders." (PMID 29751614, 2018). "Therefore, clinical and preclinical data point toward increased NPY promoting resilience, while reduced NPY in the brain is related to psychiatric disorders." (PMID 25206349, 2014).
metabolic disease (18 papers, 2015 to 2026). A congenital disorder (due to inherited enzyme abnormality) or acquired (due to failure of a metabolically important organ) disorder resulting from an abnormal metabolic process. "Animal and human studies have suggested a potential role for NPY in behavioral processes, and some have reported an association between NPY rs16147 polymorphism and metabolic disorders." (PMID 41464486, 2025). "In humans, elevated NPY levels are associated with increased risk for metabolic disorders in individuals with gain-of-function polymorphism in the NPY gene." (PMID 29674968, 2018). "NPY encodes a neuropeptide (neuropeptide Y) that is widely expressed in the nervous system and is associated with various metabolic diseases and influences many physiological processes, such as food intake, cardiovascular function, circadian rhythm, stress response, and cortical excitability." (PMID 35222524, 2022). "We studied the association of the single-nucleotide variants (SNVs) rs11100494 and rs6837793 of the NPY5R gene, and rs16147, rs5573, rs5574 of the NPY gene, with metabolic disorders in Russian patients with SSDs." (PMID 35213955, 2022). "Therefore, assessing the metabolic regulation function of Arc NPY neurons and their relationship with the physiological status of metabolic diseases has clinical significance for the prevention and treatment of metabolic-related diseases." (PMID 34307371, 2021). "However, NPY is also involved in the development of metabolic disorders without causing overeating in mouse models." (PMID 32831640, 2020). "Beyond inflammation, dysregulation of orexigenic neuropeptides such as neuropeptide Y (NPY) and melanin-concentrating hormone (MCH) worsens metabolic disease." (PMID 41409607, 2025). "Subjects with MUO have higher serum levels of NPY compared with individuals with MHO, demonstrating the crucial role of NPY in metabolic diseases." (PMID 36830982, 2023).